MIR302CHG (miR-302/367 cluster host gene)
Gene: Long non-coding RNA gene on chromosome 4 (112,646,476 to 112,706,894, reverse strand). Ensembl gene ENSG00000249532.
Gene Ontology:
Biological process: miRNA-mediated post-transcriptional gene silencing
Cellular component: RISC complex